ESR1 (estrogen receptor 1)
Diseases named in the same sentence as ESR1 in open-access papers (continued):
Sharing a sentence is not in itself a finding about the gene and the disease.
breast cancer (continued). "The phase II ELAINE-1 trial was conducted in HR+/HER2− relapsed breast cancer, with 40% of the subjects having the Y537S ESR1 mutation and progressing on prior AI and CDK4/6is; lasofoxifene was given as a single agent against fulvestrant and did not significantly prolong PFS." (PMID 40244377, 2025). "Subsequently, we tested whether the combination of CTC numbers and ESR1 mutational status in blood samples from advanced breast cancer patients can improve the clinical value of a single liquid biopsy." (PMID 40076662, 2025). "A new oral SERD, elacestrant, has more recently been developed but is currently only approved in the United States and the European Union for use in patients with ESR1-mutated ER+/HER2- breast cancer with disease progression following at least one line of endocrine therapy." (PMID 39565495, 2025). "In January 2023, Elacestrant was approved by the FDA for the treatment of advanced breast cancer patients with ESR1 mutations developed after estrogen-deprivation therapy with aromatase inhibitors in combination with CDK4/6 inhibitor, also approved by EMA in July 2023." (PMID 40507825, 2025). "DNA methylation at the ESR1 is associated with estrogen response and breast composition in adolescent females that may influence breast cancer risk in adulthood." (PMID 40406098, 2025). "To date, ESR1 activating mutations acts as key player to clinically stratify estrogen receptor (ER)+/HER2-advanced breast cancer (BC) patients eligible to novel new generation oral Selective Estrogen Receptor Degraders (SERD) relapsing after first line aromatase inhibitors." (PMID 40792231, 2025). "This double-blind, phase III trial tests whether switching from an aromatase inhibitor to the next-generation oral SERD camizestrant upon detection of an ESR1 mutation in ctDNA can delay clinical progression in HR+/HER2– advanced breast cancer." (PMID 41463084, 2025). "These ESR1 alterations are linked to hormone therapy resistance, particularly in breast cancer." (PMID 40507285, 2025). "In addition to its role in TNBC, correlation analysis using breast cancer patient datasets revealed a significant association between LURAP1L-AS1 and ESR1 expression, suggesting its broader impact across breast cancer subtypes." (PMID 39995981, 2025). "Variants in miRNA target sites within 3′UTRs may also significantly influence ESR1 regulation and the susceptibility to breast cancer." (PMID 41153361, 2025). "This phenomenon was observed in breast cancer cell lines with ESR1 mutations." (PMID 41357671, 2025). "However, breast cancer cells inevitably develop resistance to endocrine therapy through the emergence of activating mutations of the ESR1 gene from which ERα is expressed or increased signaling by multiple different receptor tyrosine kinases and c-Myc." (PMID 40206590, 2025). "For estrogen receptor-positive breast carcinoma, ctDNA surveillance can identify acquired ESR1 mutations associated with endocrine therapy resistance, with FDA approval of the Guardant360 CDx test specifically for detecting ESR1 mutations to guide elacestrant treatment decisions." (PMID 41149046, 2025). "Researchers have employed various strategies to model hotspot ESR1 mutations in breast cancer cells, including genome editing approaches such as CRISPR/Cas9 or recombinant adeno-associated viral system (rAAV, 53.3%), and conventional ectopic overexpression (33.3%)." (PMID 39702552, 2024). "Nevertheless, the significant role of ESR1 mutations in endocrine resistance was not entirely recognized until 2013, when two independent studies confirmed that somatic ESR1 mutations are relatively common (10–50%) in endocrine therapy-resistant metastatic ER+ breast cancer patients." (PMID 39767607, 2024).
breast cancer (continued). "A preclinical study showed that AZD9496 could antagonize and degrade the estrogen receptor in breast cancer cell lines, xenograft models, and patient-derived xenografts with mutations in the ESR1 gene." (PMID 38339371, 2024). "The ESR1 mutation, a mechanism of acquired endocrine resistance in breast cancer, is an example." (PMID 38473737, 2024). "In this study, we investigated ESR1 mutations as novel targets for breast cancer immunotherapy." (PMID 38335301, 2024). "The analysis of all breast cancer driver genes showed the presence of three ESR1 mutations." (PMID 38527495, 2024). "Therefore, in-depth studies should be performed to probe into the effect of Bruceine D on mutated ESR1 in breast cancer." (PMID 38215156, 2024). "Given that ESR1 alterations are typically linked with treatment resistance and are found very infrequently (approximately 3%) in primary breast cancers, the ratio of treatment-naive to treatment-exposed patients may have skewed our analysis." (PMID 39235812, 2024). "ESR1 Pvull (rs2234693) is one of the most researched polymorphisms in the ESR1 gene, which is associated with numerous diseases (e.g., cardiovascular diseases, breast cancer), and might also have an effect on BMD." (PMID 39408816, 2024). "Finally, using in vitro cytotoxicity assays, we showed the lysis of peptide-pulsed targets and breast cancer cells expressing common ESR1 mutations by expanded antigen-specific CTLs." (PMID 38335301, 2024). "Furthermore, we successfully found the HR+ breast cancer specific targeted therapy target (ESR1) based on community cohesion scores which are significantly declined in the clusters which are associated with the HR+ breast cancer samples." (PMID 38622359, 2024). "ESR1 mutations are present in about 30% of patients with metastatic breast cancer who have received aromatase inhibitors, although only in 5% of breast cancer recurring after adjuvant aromatase inhibitors, and 1% of endocrine therapy-naïve metastatic breast cancer." (PMID 38869741, 2024). "Clinical studies showed that ESR1 mutations that promote ligand-independent activation (e.g., Y537S, D538G) occur predominantly in metastatic or advanced breast cancer patients who were previously treated with estrogen deprivation therapy, especially aromatase inhibitors." (PMID 39767607, 2024). "Therefore, to link the expression pattern of the canonical luminal breast cancer markers with the ‘proliferative’ ST_2‐associated SC clusters, we further investigated our scRNA‐seq datasets using the classification based on ESR1/PGR/MKI67 expressions." (PMID 38282415, 2024). "Cyclin D1, frequently over-expressed in ESR1-mutated breast cancer, could activate the CDK4 and CDK6 to facilitate cell cycle progression through the G1 restriction point." (PMID 36624500, 2023). "The gene ESR1 codes for the estrogen receptor alpha protein and genetic variations in this gene have been reported to be associated with breast cancer and are well described in breast cancer etiology impacting cancer progression, treatment success, and long term disease outcomes." (PMID 36703164, 2023). "While AI were associated with improved outcomes compared to tamoxifen, their use as monotherapy or even in combination with CDK4/6 inhibitors for the treatment of recurrent, advanced ER+ breast cancer is limited by acquired resistance, mainly due to ESR1 mutations." (PMID 38003387, 2023). "These factors may be linked to the estrogen receptor ESR1, making it more likely to be relevant to the more aggressive form of breast cancer." (PMID 37469399, 2023). "As such, it might be investigated whether endocrine-resistant advanced breast cancer patients in whom ESR1 mutations become undetectable after chemotherapy can be successfully re-introduced to endocrine treatment." (PMID 37226020, 2023).
breast cancer (continued). "This study assessed ESR1 mRNA expression via RT-qPCR in FFPE canine mammary samples to compare data with previously investigated miR-18a and miR-18b predicted to target ERS1 mRNA, as a possible epigenetic mechanism responsible for the loss of the estrogen receptor alpha in canine mammary cancer." (PMID 36978627, 2023). "Indeed, hotspot mutations in the ESR1 gene (ERα) have been shown to emerge following the development of endocrine therapy resistance in a large fraction of breast cancer patients." (PMID 36926316, 2023). "Also, the methodology used for ctDNA assessment has already been validated in retrospective studies of circulating ESR1 mutations in breast cancer." (PMID 37924026, 2023). "To investigate the clinical impact of ESR1 mutations in cfDNA on the efficacy of chemotherapy in metastatic ER+/HER2- breast cancer patients, we analyzed plasma samples from advanced ER+ breast cancer patients that were treated with first-line paclitaxel/bevacizumab in the ATX trial." (PMID 37226020, 2023). "In addition, the gene fusion of ESR1 is also associated with the resistance of breast cancer to endocrine therapy." (PMID 37900137, 2023). "ESR1 mutations are the most important alterations resulting in resistance to aromatase inhibitor treatment, and can be found in almost 40% of metastatic breast cancer patients and in approximately 20% of patients with endocrine-resistant breast cancer." (PMID 36900131, 2023). "Therefore, targeting PI3K and mTORC1 by combining their inhibitors with endocrine therapies can be of additive efficacy in endocrine-resistant and ESR1-mutated breast cancer." (PMID 38239650, 2023). "The ELAINE 1 study explored whether lasofoxifene has better antitumor activity than fulvestrant in advanced breast cancer patients with ESR1 mutation after progression on CDK4/6 inhibitors combined with AI therapy." (PMID 38090370, 2023). "The most frequent ESCAT II alteration was the ESR1 mutation in breast cancer." (PMID 36923436, 2023). "In conclusion, our PNA-LNA-mediated PCR clamping assay is a highly sensitive and minimally invasive assay that could be a useful monitoring tool for the detection of ESR1 mutations in the cfDNA of patients with breast cancer." (PMID 37370935, 2023). "Functional analyses aimed at a mechanistic explanation for the association of SNVs at 6q25.1 with breast cancer risk were also reported, focusing on their potential role in the regulation of the expression of ESR1 and possibly additional nearby genes such as CCDC170." (PMID 36831182, 2023). "With the improvements to next-generation sequencing (NGS) technology, genomic analysis of blood samples from cancer patients has been conducted in various studies, and the detection of ESR1 mutations in circulating tumour DNA (ctDNA) in patients with breast cancer has been reported." (PMID 37370935, 2023). "On the contrary, ESR1 mutations in primary breast cancer have been reported to be extremely rare." (PMID 37174098, 2023). "ESR1 mutations in breast cancer are one of the mechanisms of resistance to aromatase inhibitors." (PMID 37174098, 2023). "ESR1 mutations were discovered in breast cancer over 30 years ago." (PMID 37835383, 2023). "Y537S and D538G mutations were found in approximately 12.7% of the primary tumors analyzed in this study, and approximately 25% of ESR1 mutations of whole exons were present in the primary tumors, which is close to the frequency of ESR1 mutations reported for recurrent breast cancers (20–50%)." (PMID 37174098, 2023). "Most metastatic-enriched cancer drivers had a cancer-type-specific enrichment, including well-established resistance gene drivers associated with anticancer therapies, such as AR and ESR1 alterations in patients with prostate and ER+ breast carcinomas treated with hormone deprivation therapies." (PMID 37165194, 2023).
breast cancer (continued). "Next, we assessed the anti-tumour role of LATS inhibitor in ERα mutant cells and observed that VT02956 exhibited advantages over 4-OHT and Fulvestrant in inhibiting the breast cancer cells that have hormone therapy resistant hot-spot mutations, including ESR1-Y537S and ESR1-D538G." (PMID 35217640, 2022). "ESR1 mutations were detected in 9 (7.4%) of 121 primary breast cancer specimens." (PMID 35501333, 2022). "ESR1 mutation has become a key mechanism of endocrine therapy resistance in breast cancer." (PMID 36077333, 2022). "Furthermore, HER2 and estrogen receptor 1 gene (ESR1) mutations are mutually exclusive in primary breast cancer, suggesting that HER2 mutations are independent predictive and prognostic markers in estrogen receptor (ER)-positive MBC." (PMID 36627899, 2022). "Experiments with breast cancer cells harboring mutations in the LBD-encoding region of the ESR1 gene have shown that mutant cells require a higher anti-estrogen drug concentration and that they proliferate in an estradiol-independent manner through constitutive activation of the ER pathway." (PMID 35501333, 2022). "Likewise, we identified a specific variant in the ESR1 gene in Breast Cancer, consistent with resistance to anti-hormone treatment." (PMID 36497297, 2022). "The Serena-6 trial evaluates whether AZD9833 (an oral SERD) plus CDK4/6 inhibitor is superior to standard therapy in HR+/HER2− advanced breast cancer with a detectable ESR1 mutation prior to progression (NCT04964934)." (PMID 36077738, 2022). "Nearly a third of all patients with metastatic ER+ breast cancer harbor ESR1 mutations." (PMID 35881485, 2022). "The presence of ESR1 mutations has been associated with poor survival in breast cancer patients." (PMID 36198774, 2022). "However, the clinical outcomes of patients with ESR1-mutated primary breast cancer are not well understood." (PMID 35501333, 2022). "ESR1, a gene that encodes estrogen receptor α (ER), had been widely studied in breast cancer." (PMID 36466554, 2022). "Importantly, this proto-signature can be refined to a simple, six-gene signature that predicts treatment response in breast cancer patients with ESR1 mutations." (PMID 36198774, 2022). "The authors of this study pointed out that increased levels of estradiol have also been shown to decrease levels of ESR1 in breast cancer and thus reasoned that the association between reduced ESR1 and high MBD may reflect high levels of plasma estradiol." (PMID 35422057, 2022). "ESR1 has been a focus in breast cancer, and its mutation is a common cause of acquired resistance." (PMID 35356272, 2022). "Moreover, high expression of the signature was strongly associated with worse survival in the Dahlgren ESR1 mutant primary breast cancer patients." (PMID 36198774, 2022). "Our analysis found enrichment of multiple gene sets that were associated with breast cancer and estrogen receptor including MORF_ESR1 (nominal p value = 0.001) and GSEA sets indicating roles in FIRESTEIN_PROLIFERATION (nominal p value = 0.001), and TAVAZOIE_METASTASIS (nominal p value = 0.001)." (PMID 35418131, 2022). "Interestingly, D538G mutant ESR1 confers estrogen-independent activity while causing additional regulatory changes in EC cells that are distinct from breast cancer cells." (PMID 35629078, 2022).
breast cancer (continued). "To recapitulate the phenotypic characteristics of tumors from ERα+ breast cancer patients harboring ESR1 mutations in a preclinical model, we employed ER+ MCF-7 cells that were genome edited using adeno-associated virus (AAV) technology to knock in the 2 most common ESR1 mutations, Y537S and D538G." (PMID 35881485, 2022). "Here, we set out to examine whether ESR1 mutations alter the “luminal-ness” and “basal-ness” balance in breast cancer cell line models and clinical specimens." (PMID 35440136, 2022). "The acquisition of ESR1 mutations in breast cancer is clearly key to the development of resistance to AI and may provide a mechanism for reduced sensitivity to anti-estrogens, including SERDs." (PMID 36198774, 2022). "In addition, ESR1 encodes an estrogen receptor involved in hormone binding, DNA binding, and transcription activation and participates in breast cancer, endometrial cancer, osteoporosis, and other pathological processes." (PMID 34178945, 2021). "Interestingly, ESR1 mutations can be found in the circulating tumor DNA (ctDNA) of metastatic breast cancer patients that relapse after AI treatment." (PMID 33741974, 2021). "In addition, the Y537S and D538G ESR1 mutations are heterozygous in the engineered mutant cell lines, more accurately reflecting the natural history of these mutations in refractory breast cancers and adding to the clinical relevance of these in vivo models." (PMID 33980285, 2021). "However, the frequency of ESR1 mutations in treatment-naïve, de novo stage IV breast cancer patients was significantly higher than that of The Cancer Genome Atlas (TCGA) results that reported that the ESR1 genomic alteration in primary tumors was < 1%31." (PMID 33692409, 2021). "Based on evidence from metastatic breast cancer, we hypothesized that early-stage breast cancers with preexisting ET-resistance ESR1 mutations would be poor responders to standard endocrine therapies." (PMID 33937624, 2021). "A majority (68.8%; 11/16) of the ESR1 mutation were detected from stage III breast cancer." (PMID 33968723, 2021). "In addition, the presence of elevated levels of ESR1 in benign breast epithelium appears to indicate an increased risk of breast cancer, and the downregulation of ESR1 results in induction of autophagy and apoptosis." (PMID 35252218, 2021). "The ESR1 mutation is involved in drug resistance and the prognosis of breast cancer, and targeting the ESR1 mutation might be a promising therapeutic strategy." (PMID 33435254, 2021). "Interestingly, the upregulation of PIAS1 is associated with epigenetic silencing of breast cancer-associated genes, including ESR1 (ERα)." (PMID 34503213, 2021). "Breast cancer risk-associated single nucleotide variants (SNVs) and somatic mutations have been mapped to luminal enhancers and other DNAse hypersensitive sites within 1 Mb of the ESR1 start site." (PMID 34831189, 2021). "Notably, loss of estrogen receptor 1 (ESR1) expression confers tamoxifen resistance, which is reported in 15–20% of breast cancer cases." (PMID 34508066, 2021). "Moreover, all breast cancers with ESR1 mutations were invasive ductal carcinomas, with a majority of luminal B subtype (75.0%, 12/16) and the remaining four patients had HER2-enriched (n=2) and triple-negative (n=2) subtypes." (PMID 33968723, 2021). "These population-based results indicate that ESR1 mutations at diagnosis of primary breast cancer occur in about 1% of women and identify for the first time in the adjuvant setting that such preexisting mutations are associated to eventual resistance to standard hormone therapy." (PMID 33937624, 2021). "If our results are replicated, ESR1 screening should be considered in ER-positive primary breast cancer, and for patients with mutated disease, ER degraders such as fulvestrant or other agents in development may be more appropriate." (PMID 33937624, 2021). "ESR1 mutation results in acquired endocrine resistance in breast cancer." (PMID 33428596, 2021).